RNU6-406P (RNA, U6 small nuclear 406, pseudogene)
Gene: Small nuclear RNA gene on chromosome 17 (43,445,507 to 43,445,613, forward strand). Ensembl gene ENSG00000252279.
Homologues: Orthologues: chimpanzee U6 (98% identical), macaque U6 (95% identical), pig U6 (68% identical), guinea pig U6 (61% identical). Paralogues in human: RNU6-116P (86% identical), RNU6-11P (86% identical), RNU6-24P (86% identical), RNU6-37P (86% identical), RNU6-43P (86% identical), RNU6-140P (85% identical), RNU6-21P (85% identical), RNU6-222P (85% identical), RNU6-33P (85% identical), RNU6-34P (85% identical), RNU6-536P (85% identical), RNU6-1 (84% identical), and 1287 more.